INS (insulin)
Diseases named in the same sentence as INS in open-access papers (continued):
Sharing a sentence is not in itself a finding about the gene and the disease.
Hypoglycemia (continued). "Other animal studies support these data by demonstrating a diminished ability to raise plasma corticosterone compared to controls following insulin-induced hypoglycemia." (PMID 30287776, 2018). "They concluded that episodes of hypoglycaemia observed in extremely low birth weight infants after several hours of insulin infusion were due to an excess of insulin after saturation of binding sites." (PMID 30114258, 2018). "This prospective, real-world study was therefore undertaken to investigate the effects of switching basal insulin to degludec in T1D patients with problematic hypoglycemia, including hypoglycemia unawareness." (PMID 29549574, 2018). "Hypoglycemia has been considered to be one of the main barriers to good glycemic control, resulting in patients becoming unwilling to optimize treatment with insulin and in clinicians conservatively recommending more aggressive treatment targets." (PMID 29721018, 2018). "ICGM systems have some advantages over FGM, such as better accuracy in the newest models of sensors, alarms in case of hypoglycemia or hyperglycemia and the possibility to connect to an insulin pump." (PMID 30060632, 2018). "Of note, almost two thirds (61.5%) of the cases of neonatal hypoglycaemia in the metformin group were in women taking insulin in addition to metformin." (PMID 29522471, 2018). "From the group of β blockers, in the view of the possible adverse reactions of β2 receptor blockade (inhibition of insulin release, masking the symptoms of hypoglycaemia), the use of β1 and selective vasodilators only (carvedilol and nebivolol) is recommended." (PMID 29805801, 2018). "There is consensus that insulin therapy and insulin secretagogues (e.g. sulfonylureas, meglitinides) due to their mode of action are the main drivers of hypoglycaemia in T2DM." (PMID 28803366, 2018). "Yet, if insulin requirements drop or hypoglycemia ensues, d-Nav makes immediate adjustments as often as needed, following the safety-first approach." (PMID 29682315, 2018). "The results demonstrated that the insulin limit strategy was effective in avoiding overnight and exercise-induced hypoglycaemia, even in the presence of an over-reading glucose sensor." (PMID 29954380, 2018). "The lower incidence of major and nocturnal hypoglycemia and flexibility of administration with premix insulin analogues have made this regimen a better choice over human premix insulins when initiating insulin therapy." (PMID 29508275, 2018). "Fear and anxiety about hypoglycaemia (see Theme 4), injection pain, and weight gain were perceived by many participants as significant mediators in insulin utilisation and included survey participants.“I am scared of needle.." (PMID 29788908, 2018). "Co-secretion of glucagon under protein-rich, carbohydrate-poor meals is thought to counteract the simultaneous effects of insulin on blood glucose levels, thus preventing dangerous glucose drops termed “hypoglycemia”8." (PMID 30013127, 2018). "The basal-bolus regimen showed improved PPG control and less hypoglycemia when compared with Regular insulin." (PMID 29508275, 2018). "Factors contributing to insulin adherence, included: being in a public place or travelling; fear of hypoglycaemia; and therapy complexity." (PMID 29788908, 2018). "According to the literature, hypoglycaemia can also be explained by an inhibition of glucose uptake in the jejunum and an increase in insulin secretion." (PMID 30257452, 2018). "Studies with both patients and HCPs (n = 5), identified hypoglycaemia, dosing irregularities, insulin adherence, and injection-related problems." (PMID 29788908, 2018). "During the experiment, two mice in the insulin injection group and one mouse in the INS/HTCC-CA/HPMCP oral group were died of hypoglycemia." (PMID 29791242, 2018). "The incidence of symptomatic hypoglycemia was reduced from 96.3% in the 6 months prior to initiating basal insulin analogues to 15.4% over the 6-month treatment period." (PMID 29460260, 2018).
Hypoglycemia (continued). "Initial plasma immunoassay insulin concentration was 1732 pmol/L, and C-peptide was 794 pmol/L during spontaneous hypoglycemia." (PMID 30085133, 2018). "37.7% were insulin users, 9.9% experienced an event of severe hypoglycemia, 9.8% were diagnosed as prefrail, and 2.6% were diagnosed as frail." (PMID 30675156, 2018). "The likelihood of this is corroborated by other published data, and as such, insulin-treated patients presenting with these symptoms should be reviewed with hypoglycaemia in mind." (PMID 28918198, 2018). "Dose adjustment seems to be further complicated by patient perceptions on insulin use which can be subjective and are influenced by factors such as avoiding hypoglycaemia and the management of wider aspects of their social and working lives." (PMID 29788908, 2018). "Driven by the protective effect of dual treatment with insulin and glucagon on hypoglycemia, we went on to determine the optimal ratio between the two hormones." (PMID 29595915, 2018). "Presentation with nausea was also more frequent in those insulin-treated patients with a recognised/reported episode of hypoglycaemia over the year: 6/27 (22.2%) vs 1/52 (1.9%), p = 0.006." (PMID 28918198, 2018). "In the patient based surveys (n = 14) these included: hypoglycaemia glycaemic control, injecting in public, problems with injections, insulin intensification, insulin adherence, and perceptions of T2DM." (PMID 29788908, 2018). "It is unclear if these gene expression changes reflect compensatory efforts to counter the excessive insulin production that develops neonatally and protect against hypoglycemia, or a bonafide effect of endothelial cells in instructing mature β-cell phenotype." (PMID 30303066, 2018). "In our case, after discontinuation of captopril, an initial decrease in insulin autoantibody levels was observed followed by improvement in episodes of hypoglycemia." (PMID 30462811, 2018). "In this series, the first clue to IAS came from high insulin concentrations and insulin/C-peptide molar ratios in samples drawn during hypoglycemia." (PMID 30085133, 2018). "Hypoglycemia is a well-known potential adverse event for individuals on insulin and oral diabetic medications." (PMID 29799604, 2018). "For instance, a liver–brain axis that is responsive to liver glycogen content was recently demonstrated to modulate the counterregulatory response (CRR) to insulin-induced hypoglycaemia." (PMID 29417183, 2018). "Fasting and insulin-induced hypoglycaemia have been found to increase PPO mRNA in the rat lateral hypothalamic area." (PMID 30477546, 2018). "Longer-term prospective cross-over studies with a large number of subjects are needed to confirm the true differences between the insulin regimens, especially of hypoglycemia frequency." (PMID 30127860, 2018). "We believe that hypoglycemia is one vital adverse event that deserves more attention when antidiabetic agents are added to insulin therapy." (PMID 29507862, 2018). "This allows patients to adjust insulin therapy to fit their changing needs while preventing hypoglycemia." (PMID 32685571, 2018). "In this study two individuals were able to discontinue insulin for oral hypoglycaemia treatment, demonstrating the potential benefits of making a molecular diagnosis." (PMID 29666556, 2018). "The variables that most explained the heterogeneity were bolus insulin (26%) and definition of hypo (14%) for general hypoglycemia, cross-over design (23%) and intervention brand (13%) for nocturnal hypoglycemia, and Jadad score (16%) for A1C." (PMID 29649221, 2018). "In this paper, we propose a wearable non-invasive system that targets insulin-dependent diabetics and that is able of detecting efficiently and at low cost the nocturnal hypoglycaemia." (PMID 30568801, 2018). "Because this mechanism of action works independently of insulin, SGLT2 inhibitors are complementary to other AHA classes (including insulin) and have an inherently low risk of hypoglycemia." (PMID 29411292, 2018).
Hypoglycemia (continued). "Pulmonary administration of TI addresses many of the limitations of SC insulin and has been shown to improve glycemia in insulin-naïve T2D individuals, consistently demonstrating less hypoglycemia than SC insulin." (PMID 29707584, 2018). "Two studies reported severe hypoglycaemia, five reported total insulin, three reported BMI, and one reported blood glucose." (PMID 29596460, 2018). "It is important to remember that sepsis can increase glucose utilization while renal failure can decrease insulin clearance, both leading to hypoglycemia." (PMID 29849273, 2018). "At the time of hypoglycemia (blood glucose 1.4 mmol/l), an inappropriate glycemic response to glucagon (increase of 4.3 mmol/l) was consistent with excess insulin action, confirming hyperinsulinism." (PMID 30005691, 2018). "The primary outcome was HbA1c and secondary outcomes were severe hypoglycaemia, total daily insulin, BMI, quality of life and mean daily glucose." (PMID 29596460, 2018). "This pioneer study documents an increase in insulin expression and an increase in islet size in P. falciparum malaria patients with hypoglycaemia." (PMID 29993021, 2018). "Counselling/education about SMBG and hypoglycemia prevention, recognition, and treatment is recommended to all patients initiating with insulin." (PMID 29527102, 2018). "Minor hypoglycemia rates of 1.08 and 2.56 ppy were prospectively observed in the insulin detemir and insulin glargine group, respectively, in the Turkish T2DM cohort from the observational SOLVE study." (PMID 29433560, 2018). "Insulin users and individuals that experienced a severe hypoglycemia episode were less likely to be in the highest 6-minute walk quartile." (PMID 30675156, 2018). "As this manual (or open‐loop), insulin therapy is based on irregular glucose measurement, thus at certain instances, due to improper insulin dosages, glucose concentration can drastically fall <50 mg/dl, leading to a situation called hypoglycaemia." (PMID 30259867, 2018). "Likewise, the risk of hypoglycemia may impact on the adherence of SU and insulin." (PMID 29391064, 2018). "Sirt6-deficient mice die about 4 weeks of age, exhibiting severe metabolic defects, including low insulin and hypoglycemia." (PMID 30574122, 2018). "The heterogeneity in general hypoglycemia was explained in 26.13% by bolus insulin (p = 0.01), in 13.96% by hypoglycemia definition (p = 0.10), and in 7.16% by duration of study (p = 0.10)." (PMID 29649221, 2018). "Detailed assessments of hypoglycaemia timing, incidence and other characteristics during home use of closed‐loop insulin delivery are undocumented." (PMID 29577536, 2018). "Using EMR data from a large patient population, we developed a model to predict biochemical and clinically significant hypoglycemia in hospitalized patients treated with subcutaneous insulin." (PMID 29527311, 2018). "Of note, incretin-based therapies were administered with insulin in 10 of the 14 studies reporting hypoglycaemia." (PMID 30428906, 2018). "Considering general hypoglycemia, the meta-analysis showed a statistically significant difference between the insulin analogue and NPH (RR = 0.95; 95% CI 0.91; 0.99; I2 97.5%)." (PMID 29649221, 2018). "Insulin-induced hypoglycemia increases sGC s-nitrosation and VMH injection with a nitrosating agent impairs the CRR." (PMID 29593556, 2018). "Both the hypoglycemia and low insulin would be consistent with diminished food intake, which is examined in more detail below." (PMID 29466436, 2018). "Data from the ITR-QOLN questionnaire further suggested that uncontrollable hypoglycemia, especially nocturnal hypoglycemia, was a major concern among insulin users and that IDegAsp slightly reduced this concern." (PMID 30127860, 2018). "The principal factors associated with insulin omission were low socioeconomic status, fear of hypoglycemia, and a greater number of insulin applications per day." (PMID 30116737, 2018).
Hypoglycemia (continued). "They observed that the decrease in serum potassium during insulin-induced hypoglycemia had a two-stage process with an initial fall and an additional decline, which was prevented in subjects given propranolol." (PMID 30105256, 2018). "To date, use of standard CGM has shown reductions in time in hypoglycaemia (sensor glucose <3.9 mmol/l) but usually in mixed insulin therapy cohorts." (PMID 29273897, 2018). "It is also possible that any or all of these sensors play a role in the inhibition of insulin secretion during hypoglycemia." (PMID 29593556, 2018). "The IRs of severe hypoglycemia were highest in T1DM patients using pre-mix insulin in the 4-week prospective period (19.6 ppy) and lowest in T1DM patients using long-acting insulin in the 6-month retrospective period (1.2 ppy)." (PMID 29433560, 2018). "The patient-centred themes were: insulin-related beliefs, social influences, psychological factors, hypoglycaemia, and therapy barriers." (PMID 29788908, 2018). "The odds ratio for insulin-treated patients having a hypoglycaemia episode if they had consulted on another occasion with a possible “hypo clue” symptom, was 4.2, compared to 1.1 in sulphonylurea or metformin only-treated patients." (PMID 28918198, 2018). "Hypoglycemia prompts an integrated response involving reduction in insulin release and secretion of key counter-regulatory hormones glucagon and epinephrine that together promote endogenous glucose production to restore normoglycemia." (PMID 30146176, 2018). "Studies with PACAP-deficient mice have shown a more profound and longer lasting insulin-induced hypoglycemia and a reduction in glucose-stimulated insulin secretion." (PMID 30088106, 2018). "Twice-daily insulin detemir in a basal-bolus regimen showed less nocturnal hypoglycemia and improved glycemic control in several studies." (PMID 29508275, 2018). "Patients increased glucose monitoring, consulted a doctor/nurse, and/or reduced the insulin dose in response to hypoglycemia." (PMID 29524189, 2018). "Even so, more “hypo clue” consultations were seen in insulin-treated patients who had also had a documented episode of hypoglycaemia." (PMID 28918198, 2018). "Augmenting an insulin pump with glucose sensor information leads to improved outcomes: decreased haemoglobin A1c levels, increased time in glucose target and less hypoglycaemia." (PMID 30509293, 2018). "Multiple clinical studies have been performed with closed loop insulin delivery devices and have shown an improvement in overall glycemic control and time spent in hypoglycemia." (PMID 30250968, 2018). "At birth, patients with RMS also show fasting hypoglycemia due to severely increased insulin levels, but with progression of the disease, insulin levels decline." (PMID 29695048, 2018). "As a result of less insulin use, hypoglycemia event rates were lower with canagliflozin 300 mg versus dapagliflozin 10 mg." (PMID 29411292, 2018). "Patients in the NPH insulin group had more hypoglycemia in the year before cohort entry (21.0% versus 4.1%) and higher frequency of one or more comorbidity." (PMID 29713649, 2018). "Hypoglycemia resolved over the subsequent 4 weeks, with anti-insulin IgG falling to 5 mg/L, plasma insulin to 322 pmol/L, and C-peptide to 1210 pmol/L, although insulin recovery after PEG precipitation increased only modestly to 17%." (PMID 30085133, 2018). "In this study, insulin expression was prominent in the group of P. falciparum malaria patients with hypoglycaemia, and those with BS = 40–120 mg/dl, compared to the control group (P = 0.014 and P = 0.011, respectively)." (PMID 29993021, 2018). "Glucose excursion was assessed prior to and post hypoglycaemia to increase understanding of hypoglycaemia incidence and recovery during hybrid closed‐loop insulin delivery." (PMID 29577536, 2018).
Hypoglycemia (continued). "The following study is performed to determine the frequency of hypoglycemia recurrence leading to return ED visits among individuals discharged from the ED who are taking insulin (long and short acting) and oral diabetic medications." (PMID 29799604, 2018). "Contributors to suboptimal adherence to insulin treatment include pain, inconvenience, and regimen complexity; however, a key driver is hypoglycemia." (PMID 29707584, 2018). "Fasting blood glucose (FBG), 2-hpostprandial glucose (2hPG), glycosylated hemoglobin (HbA1c), body mass index (BMI), daily insulin dose, and hypoglycemia events were assessed." (PMID 30285711, 2018). "Current clinically available methods of insulin replacement cannot prevent the occurrence of frequent hypoglycaemia and diabetic complications." (PMID 29306997, 2018). "Thirty-six adults with T1D (all participants had a c-peptide of less than 200 pmol/L) on intensified multiple daily insulin injections and with impaired awareness of hypoglycemia or a recent episode of severe hypoglycemia were included." (PMID 30265562, 2018). "We identified systematic reviews of RCTs that evaluated the efficacy of LAIA glargine or detemir, compared to NPH insulin for T1D, assessing glycated hemoglobin (A1C) and hypoglycemia." (PMID 29649221, 2018). "We also reviewed the difference in weight, basal insulin requirements, hypoglycemia, and patient satisfaction questionnaire at one year." (PMID 30410846, 2018). "In patients with T1D, switching to degludec was associated with an improvement in HbA1c and reductions in basal insulin dose, severe hypoglycemia, and DKA." (PMID 29549574, 2018). "In ITT, the simulated hypoglycemia response to insulin, by adult rats was delayed and attenuated, evidencing an insulin resistant state." (PMID 30374065, 2018). "Since insulin needs to be reduced with light to moderate exercise intensity to avoid peri-exercise hypoglycemia, glucose levels remain relatively stable during exercise with vigorous intensity and rise immediately after intense exercise is performed." (PMID 30333794, 2018). "Two studies reported the effect of a low-carbohydrate diet on frequency of severe hypoglycaemia, five studies reported total daily insulin, three studies reported BMI, and one study reported mean daily blood glucose." (PMID 29596460, 2018). "For hypoglycemia prevention during and after exercise, it has been suggested that closed loop systems should include both insulin and glucagon so that they can more closely replicate the hormonal changes that usually take place." (PMID 30524371, 2018). "The insulin‐dose resulting in hypoglycemia was increased four times: from 40 nmol/kg insulin alone to 160 nmol/kg insulin in the presence of the glucagon‐analogue." (PMID 29595915, 2018). "Spanish authors described a case of symptomatic hypoglycemia in T2DM hepatitis C patient at 18th day of sofosbuvir/ledipasvir treatment despite radical decrease of insulin dosage." (PMID 30402450, 2018). "Recurrent exposure to insulin-induced hypoglycemia can lead to the development of HAAF (a life-threatening metabolic disorder associated with blunted hypoglycemic counter-regulation)." (PMID 29931424, 2018). "While dual hormone systems have generally been more successful at hypoglycemia prevention during exercise when compared to systems using insulin alone, they still cannot fully prevent hypoglycemia." (PMID 30524371, 2018). "The majority of patients (27/33, 81.8%) with at least one documented episode of hypoglycaemia were insulin-treated." (PMID 28918198, 2018). "Prior exposure to insulin-induced hypoglycemia was shown to increase glial acetate metabolism (GAM) during subsequent exposure to hypoglycemia in diabetic individuals." (PMID 29931424, 2018). "After 6 months of basal insulin analogue treatment, the incidence of symptomatic hypoglycemia was substantially lower, affecting 71 subjects (15.4%; p < 0.001 vs. 6 months before insulin analogue treatment)." (PMID 29460260, 2018).